ACE (angiotensin I converting enzyme)
Diseases named in the same sentence as ACE in open-access papers (continued):
Sharing a sentence is not in itself a finding about the gene and the disease.
preeclampsia (28 papers, 2009 to 2025). Preeclampsia is a hypertensive disorder of pregnancy that is characterized by new-onset hypertension with proteinuria presenting after 20 weeks of gestation, and depending on mild or severe forms may initially present with severe headache, visual disturbances, and hyperreflexia. "Nevertheless, a significant association was observed between the fetal ACE rs4646994 polymorphism and preeclampsia in a dominant genetic model." (PMID 39194706, 2024). "The frequency of DD homozygous genotype in the GDM PE+ group is higher than that in the GDM PE- group (24.3% vs 11.1%).The association analysis revealed the association between ACE gene I/D polymorphism and preeclampsia." (PMID 33456632, 2020). "Our study revealed a statistically significant association between the DD homozygous type of ACE gene I/D polymorphism and preeclampsia in GDM women in the general inheritance model." (PMID 33456632, 2020). "Our meta-analysis demonstrated that the polymorphisms of AGT T704C and ACE I/D were significantly associated with an increased risk of preeclampsia (PE) and weak associations of the AT1R A1166C polymorphism with PE were observed." (PMID 33230614, 2020). "The particular features in the frequency array of alleles and genotypes of the ACE gen I/D polymorphism under review, as associated with preeclampsia development risk in pregnant women with GDM, were identified." (PMID 33456632, 2020). "The available reference data on the study of the ACE gen I/D polymorphism association with preeclampsia is inconsistent." (PMID 33456632, 2020). "An interaction between the AGT T704C and ACE I/D polymorphisms and the risk of severe preeclampsia or the time onset of PE were observed, but these were not analyzed in any former meta-analysis." (PMID 33230614, 2020). "Despite numerous genetic studies conducted in different populations, to the best of our knowledge, only one study reported the association of angiotensin-converting enzyme (ACE) gene I/D variant with preeclampsia in Pakistani population." (PMID 31646966, 2019). "The ACE I/D polymorphism affects uteroplacental and umbilical artery blood flows in women with preeclampsia." (PMID 24991435, 2014). "It was concluded that in women with a history of preeclampsia the ACE I/D polymorphism affects both uteroplacental and umbilical blood flows and the recurrence of preeclampsia." (PMID 24991435, 2014). "The ACE I/D polymorphism seemed to affect the uteroplacental and umbilical artery (UA) blood flows and the recurrence of preeclampsia." (PMID 24991435, 2014). "In this study, 120 preeclamptic and 116 normotensive Turkish pregnant women were genotyped for ACE I/D polymorphism and the distribution of genotype and allele frequencies of this polymorphism in preeclampsia and controls were evaluated." (PMID 22545216, 2012). "We detected differences in genotype distribution between preeclampsia and controls for the ACE gene polymorphism when data were evaluated using a dominant model, considering DD frequency versus DI+II and using a codominant model." (PMID 22545216, 2012). "The results of previous studies on association of ACE I/D polymorphism with preeclampsia were conflicting presumably attributable to differences in study population, genetic backgrounds, and size of study groups." (PMID 22545216, 2012). "For ACE I/D polymorphism, the frequency DD genotype was 43.3% in preeclampsia, while it was 26.3% in controls analyzing data under a codominant model." (PMID 22545216, 2012). "The present study showed an association between ACE DD genotype and preeclampsia in Turkish population." (PMID 22545216, 2012). "In a meta-analysis involving 1121 patients with preeclampsia and 1361 controls from 11 studies, the ACE DD genotype was associated with increased risk of preeclampsia (OR95%CI=1.51 1.17-1.94)." (PMID 23049672, 2011). "However, the fetal ACE rs4646994 polymorphism was significantly associated with preeclampsia risk in a dominant model." (PMID 39194706, 2024).
preeclampsia (continued). "Variants of ACE have been reported to be associated with preeclampsia risk." (PMID 39194706, 2024). "Therefore, the present study aimed to investigate a relationship between ACE gene I/D polymorphism and preeclampsia development in the case of GDM in the Russian population." (PMID 33456632, 2020). "The available data suggests that increased ACE activity due to deletion (D)/insertion (I) in the 16th intron of ACE gene, which is called ACE gene I/D polymorphism, is associated with preeclampsia and varies depending on the studied population and the geography." (PMID 33456632, 2020). "Therefore, this study was aimed at investigating the relationship between I/D polymorphism of ACE gene and preeclampsia in the case of GDM." (PMID 33456632, 2020). "The differences in the data derived from different studies on the association between ACE gene I/D polymorphism and preeclampsia are likely to be due to the size, population features and the ethnicity of the study groups and also depend on the analytical inheritance model selection." (PMID 33456632, 2020). "We have confirmed that the preeclampsia risk associated with the ACE D-allele may largely be a result of publication bias." (PMID 25516509, 2014). "In a study women with preeclampsia (n = 106) were genotyped for the ACE I/D polymorphism." (PMID 24991435, 2014). "Some investigators have reported in women from various geographical origins an association between the ACE D allele or DD genotype and increased risk of preeclampsia or pregnancy-induced hypertension, whereas others could not." (PMID 22545216, 2012). "Preeclampsia pathogenesis has been associated with dysfunction of the renin-angiotensin-aldosterone (R-A-A) axis, resulting in decreased renin levels, increased angiotensin-converting enzyme (ACE) activity, decreased angiotensin II levels, and increased response to this enzyme." (PMID 35198246, 2022). "Therefore, in the present study we hypothesized that the ACE I/D polymorphism could affect placental and umbilical vasculature leading to susceptibility of preeclampsia in Pakistan." (PMID 31173490, 2019). "Drug treatment options in preeclampsia are limited because some antihypertensive drugs, such as angiotensin converting enzyme (ACE) inhibitors and angiotensin II receptor (AT1) antagonists (sartans), have shown teratogenic effects on the fetus." (PMID 33652665, 2021). "ACE levels were significantly decreased in women with preeclampsia compared with levels measured in women with normal pregnancies (P < 0.001)." (PMID 33101066, 2020). "Preeclampsia (PE) is a common pregnancy-related complication, and polymorphisms in angiotensinogen (AGT), angiotensin-converting enzyme (ACE), and angiotensin II type 1 receptor (AT1R) are believed to contribute to PE development." (PMID 28698595, 2017). "The findings from the meta-analysis revealed no statistically significant connection between the fetal ACE rs4646994 polymorphism and preeclampsia in the additive and recessive models." (PMID 39194706, 2024). "Drug treatment options in preeclampsia are limited because of the tendency of some antihypertensive drugs, such as angiotensin-converting enzyme (ACE) inhibitors and angiotensin II receptor (AT1) antagonists (sartans), to cause teratogenic effects on the fetus." (PMID 36355514, 2022). "The distribution of genotype and allele frequencies in the I/D polymorphic locus of the ACE gen matched the one expected in the Hardy-Weinberg equilibrium, both for the pre-eclampsia group and for the control (no preeclampsia) group." (PMID 33456632, 2020). "It is noteworthy that no studies of the association between ACE gene I/D polymorphism and preeclampsia development in GDM pregnant women have been conducted in the Russian population so far." (PMID 33456632, 2020).
preeclampsia (continued). "Some investigators reported that women residing in different regions had an association between ACE gene D-allele or DD genotype and a high preeclampsia risk, but others noted there was no such association with PE risk." (PMID 33456632, 2020). "Interestingly, levels of AII and ACE were increased in the maternal-placental-circulation in preeclampsia." (PMID 28430615, 2017). "In this situation, the definitive therapy for preeclampsia has been completed (delivery), and ACE inhibitors can be instituted without concern of risk of fetotoxicity of antenatal ACE inhibitor exposure." (PMID 20814538, 2010). "In preeclampsia, a potentially life-threatening complication characterised by maternal hypertension and multi-organ failure, ACE2 activity reflected by the ACE2:ACE ratio is higher than normal, impairing placental development and function." (PMID 39920116, 2025).
urticaria (28 papers, 2008 to 2025). A vascular reaction of the skin characterized by erythema and wheal formation due to localized increase of vascular permeability. "When triggered by ACE inhibitors, a notable feature is the absence of itching or urticaria, with the presence of urticaria suggesting diverse underlying causes." (PMID 38543146, 2024). "Similar to urticaria, allergic and non-allergic origins are causable and, especially, angiotensin converting enzyme (ACE) inhibitor can be a trigger." (PMID 32256502, 2020). "AE due to ACE inhibitor or NSAID use may present without urticarial involvement or in concurrence with chronic spontaneous urticaria, which is defined as urticaria occurring for at least six weeks due to an endogenous cause and not external physical stimuli." (PMID 25670937, 2014).
colorectal cancer (27 papers, 2010 to 2026). A primary or metastatic malignant neoplasm that affects the colon or rectum. "The colocalisation analyses of ACE inhibition and colorectal cancer risk found strong evidence that there is a shared causal variant in this region (posterior probability H4=0.94)." (PMID 41085561, 2026). "We found strong evidence that genetically proxied inhibition of ACE increased colorectal cancer risk." (PMID 41085561, 2026). "We found strong evidence that genetically proxied ACE inhibition had an adverse effect on colorectal cancer risk, supported by genetic colocalisation of these traits around the ACE gene region." (PMID 41085561, 2026). "We found evidence for associations of genetically-proxied elevated omega-3 fatty acids (OR 1.10; 95% CI 1.03, 1.18; p=6.20x10-3) and reduced plasma ACE levels (OR 1.08; 95% CI 1.03, 1.13; p=9.36x10-4) with colorectal cancer risk." (PMID 41085561, 2026). "Specifically, additional epidemiological evidence with non-overlapping sources of bias is needed to further evaluate the association between ACE inhibition and colorectal cancer risk, ideally with evidence from RCTs." (PMID 41085561, 2026). "Reduced plasma ACE levels were robustly linked to increased colorectal cancer risk, and there was some evidence to support that elevated calcium and progesterone (in men) were inversely associated with colorectal cancer." (PMID 41085561, 2026). "As this finding was generated using an alternative methodology and was consistent with the current study, it provides “triangulation” of the link between genetically proxied ACE inhibition and colorectal cancer risk." (PMID 41085561, 2026). "We found strong evidence that a decrease in plasma ACE levels, the mechanism of action of ACE inhibitors, increased colorectal cancer risk (OR per unit decrease in inverse-rank normalized protein expression: 1.08; 1.03, 1.13; 9.36x10-4)." (PMID 41085561, 2026). "Data concerning ACE inhibitors and the risk for cancer are conflicting, with a recent report indicating null associations between use of ACE inhibitors and colorectal cancer risk." (PMID 37933755, 2023). "Further work is warranted to unravel molecular mechanisms underpinning the association of ACE with colorectal cancer risk." (PMID 35113855, 2022). "Colocalization analysis suggested that serum ACE and colorectal cancer associations had a 91.4% posterior probability of sharing a causal variant within the ACE locus." (PMID 35113855, 2022). "Genetically proxied ACE expression in the colon was associated with increased odds of colorectal cancer (OR per SD increase in expression: 1.02, 95% CI 1.00 to 1.04; P = 0.01)." (PMID 35113855, 2022). "The potential mechanisms underpinning an association between genetically proxied ACE inhibition and colorectal cancer risk are unclear." (PMID 35113855, 2022). "Through colocalization analyses, the authors went on to show that a shared variant within the ACE locus was likely to be related to both circulating ACE protein levels and colorectal cancer risk." (PMID 35113864, 2022). "We found evidence that genetically proxied inhibition of the drug target for ACE inhibitors was associated with an increased risk of colorectal cancer." (PMID 35113855, 2022). "While the observed association between genetically proxied ACE inhibition and increased colorectal cancer risk warrants further investigation, there are a number of important reasons why it should not currently affect clinical practice." (PMID 35113864, 2022). "Genetically proxied ACE inhibition was associated with an increased odds of colorectal cancer (OR equivalent to 1 mm Hg lower SBP: 1.13, 95% CI 1.06 to 1.22; P = 3.6 × 10−4)." (PMID 35113855, 2022). "The quinoa peptides with MW < 5 kDa also have exhibited antihypertensive activity via inhibiting the activity of ACE, and the ACE inhibitors have been shown to be associated with the colorectal cancer risk in a duration-response manner." (PMID 35053925, 2022).
colorectal cancer (continued). "A meta-analysis of 7 observational studies reported a protective association of ACE inhibitor use with colorectal cancer risk (OR 0.81 95% CI 0.70 to 0.92), though with substantial heterogeneity across studies (I2 = 71.1%)." (PMID 35113855, 2022). "On the other hand, we also previously reported that higher circulating levels of the angiotensin-converting enzyme (ACE) is associated with a better response to anti-angiogenic treatment with bevacizumab in breast- and colorectal-cancer patients." (PMID 35804826, 2022). "In this study, we observed that genetically proxied long-term ACE inhibition was associated with an increased risk of colorectal cancer, warranting comprehensive evaluation of the safety profiles of ACE inhibitors in clinical trials with adequate follow-up." (PMID 35113855, 2022). "Genetically proxied ACE inhibition equivalent to a 1-mm Hg reduction in SBP was associated with increased odds of colorectal cancer (odds ratio (OR) 1.13, 95% CI 1.06 to 1.22; P = 3.6 × 10−4)." (PMID 35113855, 2022). "Our mendelian randomization analyses suggest that genetically proxied long-term inhibition of ACE is associated with increased risk of colorectal cancer." (PMID 35113855, 2022). "Findings for genetically proxied ACE inhibition and colorectal cancer risk were replicated in an independent sample of 1,571 colorectal cancer cases and 120,006 controls of European ancestry in the Finngen consortium (1.40, 95% CI 1.02 to 1.92; P = 0.035)." (PMID 35113855, 2022). "In this mendelian randomization analysis of up to 289,612 cancer cases and 291,224 controls, genetically proxied long-term ACE inhibition was associated with an increased risk of colorectal cancer." (PMID 35113855, 2022). "Reduced plasma ACE levels were robustly linked to increased colorectal cancer risk." (PMID 41085561, 2026). "For ACE, omega-3 fatty acids and calcium, all SNPs were found to explain more of the variance in the molecular trait, consistent with the molecular trait causally influencing colorectal cancer." (PMID 41085561, 2026). "Limited statistical power in analyses of genetically proxied ACE inhibition and colorectal cancer risk in East Asians (instrumented by rs4343) may also have accounted for the lack of association between these traits within this population." (PMID 35113855, 2022). "Using genetic variants related to blood pressure at the ACE gene, the authors found genetic evidence supporting an effect of angiotensin converting enzyme (ACE) inhibition on increased risk of colorectal cancer in UK Biobank participants of European genetic ancestry." (PMID 35113864, 2022). "Finally, findings from this analysis should be “triangulated” by employing other epidemiological designs with orthogonal (i.e., nonoverlapping) sources of bias to each other to further evaluate the association of ACE inhibition and colorectal cancer risk." (PMID 35113855, 2022). "Despite the evidence suggesting a link between genetically proxied ACE inhibition and colorectal cancer, however, these findings cannot demonstrate a causal relationship between ACE inhibitor use and colorectal cancer risk; only a randomized controlled trial could establish this relationship." (PMID 35113855, 2022). "However, multivariable mendelian randomization analysis examining the association of genetically proxied ACE inhibition with colorectal cancer risk adjusting for CYB561 expression in the colon was consistent with univariable analyses (OR 1.13, 95% CI: 0.96 to 1.32; P = 0.14)." (PMID 35113855, 2022). "Although there is MR evidence showing the potentially harmful effects of ACE inhibitors on colorectal cancer, of BBs on hepatocellular carcinoma, and of CCBs on prostate cancer, meta-analysis of RCTs consistently reported null." (PMID 39567981, 2024). "Blockade of the renin angiotensin system (RAS) via angiotensin I converting enzyme (ACE) inhibition reduces growth of colorectal cancer (CRC) liver metastases in a mouse model." (PMID 20380732, 2010).